NFATC1 (nuclear factor of activated T cells 1)
Diseases named in the same sentence as NFATC1 in open-access papers (continued):
Sharing a sentence is not in itself a finding about the gene and the disease.
tumor (continued). "The blockade of CXCL8 or NFATc1 largely attenuated neutrophil infiltration, NET formation, and tumor promotion induced by SKAP1." (PMID 39269257, 2024). "Another GRN had high activity for IRF2, along with NFATC1/2 and EGR2, consistent with our recent report of tumor–intrinsic inflammatory JAK/STAT signaling and inflammatory programs driving lineage plasticity (labeled as IRF2+ Inflam)." (PMID 38645034, 2024). "NFATC1 increase BLCA to promote tumor cell growth/colony formation, and can also promote tumor migration and invasion by providing the expression of MMP2 and MMP9." (PMID 38910160, 2024). "Furthermore, we evaluated the association between nuclear NFATc1 expression in the tumor cells of 91 patients who received first-line HPE (59 patients with HPE responsiveness and 32 without HPE responsiveness) and HPE responsiveness and CagA expression in tumor cells." (PMID 39558403, 2024). "TalaA downregulated the phosphorylation of a series of transcription factors, including JUN, NFATC1, EIF4EBP1, ABL, RPS6KB1, and EIF4ENIF1, most of which play pivotal roles in cell proliferation and tumor progression." (PMID 37866481, 2023). "Furthermore, osteoclastogenesis induced by OSCC cells did not correlate with the upregulation of NFATc1 expression, and tumor-induced osteoclastogenesis, which targets OPCs, was caused by unknown mechanisms." (PMID 36614130, 2022). "In previous studies, nuclear factor of activated T-cells 1 (NFAT1), acting as a Ca2+-dependent transcription factor, was found to be able to promote the expression and secretion of TGFβ to promote tumor metastasis." (PMID 35361751, 2022). "Among various NFATs, NFATc1 (NFAT2) and NFATc2 (NFAT1) seemed to be essential for the regulation of tumor related functions, including cell survival/proliferation, invasive migration and angiogenesis." (PMID 34187410, 2021). "The staining of a BC tumor microarray (TMA) with 119 different samples revealed that the majority of the tumor samples expressed moderate levels of EZH2 and high levels of NFATc1." (PMID 34845197, 2021). "Nfatc1 retained our attention as it was shown to promote EMT and tumor progression in several tumor entities." (PMID 34845197, 2021). "Some tumor-related genes such as FOX, NFATC1 and JUN were highly expressed in Nthy-ori 3-1 with lentivirus vector PDS159-FAM172A and FTC tissues compared with Nthy-ori 3-1 with empty vector and peri-carcinoma tissues." (PMID 33095186, 2020). "CD36 (p value < 2.22e-16), CPA3 (p value < 2.22e-16), NFATC1 (p value = 9.1e-08), and RASGRP2 (p value < 2.22e-16) were highly expressed and SLC2A3 (p value = 0.0015) was lowly expressed in tumor samples." (PMID 32908876, 2020). "Accordingly, we have previously demonstrated a pivotal role of NFATc1 in pancreatic carcinogenesis and PDAC progression where the TF strongly promotes tumor cell proliferation, invasion, metastasis, and acquisition of stemness features in vitro and in vivo." (PMID 31171768, 2019). "NFATC1, NFATC2, NFATC3, NFATC4, and NFAT5 were all highly expressed in the tumor tissue of the TCGA dataset compared with normal tissue of the GTEx dataset." (PMID 31827081, 2019). "In conclusion, NFATc1 is frequently inactivated in HCC and functions as a tumor suppressor in liver carcinogenesis." (PMID 30085405, 2018). "Here the authors show NFATc1 controls the cytotoxicity and metabolic switching of activated CD8+ T cells required for optimal response to bacteria and tumor cells." (PMID 28894104, 2017). "WT and Nfatc1−/− CTLs generated from CD8+ T cells of C57/BL6 mice by co-culture with irradiated Balb/c splenocytes for 6 d and A20J tumor cells as targets revealed a 40% decrease in killing, compared to WT CTLs." (PMID 28894104, 2017).
tumor (continued). "Copy number alterations of MYC (8q24.21), FHIT (3p14.2), WDR60 (7q36.3), COL4A2 (13q34), NFATC1 (18q23), and NCOA3 (20q12) were analyzed in six matched tumor and normal tissue pairs (268–1, 271–1, 272–2, 301–1, 685–1 and 685–2)." (PMID 26360582, 2015). "HF stem cell markers such as Nuclear factor of activated T-cells, cytoplasmic 1 (NFATc1), CD34 and Prominin-1/CD133 are all known to contribute in regulating epidermal stem cell quiescence, location, proliferation, wound healing and in tumor formation." (PMID 22383956, 2012). "Furthermore, NFATc1 upregulates MDM2, which not only enhances metabolic reprogramming but also facilitates cell cycle progression, thereby further promoting tumor proliferation." (PMID 41203626, 2025). "Through rescue experiments combining NFATc1 knockdown with MDM2 overexpression, we observed a partial reversal of the NFATc1 knockdown-induced suppression of both cell proliferation and tumor growth." (PMID 41203626, 2025). "Additionally, NFATc1 knockdown or CHIP overexpression, which resulted in a decrease in DDIAS levels, promoted apoptosis and inhibited tumor development in lung cancer." (PMID 37121974, 2023). "Tumours expressing P2X7R are also characterised by increased proliferation, decreased apoptosis, and high levels of the transcription factor nuclear factor of activated T cells 1 (NFATc1)." (PMID 35267424, 2022). "With NFATc1, we identified a previously unknown inducer of EZH2 expression in PDAC development and progression and demonstrated that the tumor-promoting transcription factor directly targets the EZH2 gene for transcriptional activation." (PMID 34943970, 2021). "Similarly, EO771 tumor cell-derived CM increased the number of TRAP-positive RAW264.7 osteoclasts with elevated levels of cathepsin K and NFATc1 in 5 days." (PMID 34830748, 2021). "Therefore, our outcomes showed critical roles for miR‐338/ NFATc1 axis in the pathogenesis of NSCLC and suggested its possible application in tumor treatment." (PMID 31823518, 2020). "In contrast to previous reports and consistent with a concept of retained tumor suppressive TGFβ activity, even in established PDAC, TGFβ treatment reduced PDAC cell proliferation and promoted apoptosis even in the presence of oncogenic NFATc1." (PMID 31171768, 2019). "We also demonstrated that tumor-induced osteoclastogenesis occurred without the significant up-regulation of NFATc1." (PMID 31835378, 2019). "We analyzed NFATc1 protein expression levels in 81 pairs of HCC tumor (T) tissues and corresponding adjacent nontumor (NT) tissues, as well as 20 normal (N) liver tissues, by immunohistochemistry (IHC)." (PMID 30085405, 2018). "As NFATc1 was downregulated in HCC, we investigated whether ectopic expression of NFATc1 could restore its tumor suppressor function and inhibit tumor growth." (PMID 30085405, 2018). "The median survival in the 44 patients whose tumor was negative for nuclear NFATc1 expression was 69.8 months compared to 53.2 months in the 46 patients whose tumor showed positive nuclear NFATc1 expression." (PMID 26795951, 2016). "In particular, NFATC1 may act as an oncogenic factor, whereas NFATC2 acts as a tumor suppressor." (PMID 34309232, 2021). "Hence, in our study, we investigated NFAT family expression in HCC and adjacent nontumor tissues and found that NFATc1 abundance was very different between tumor and nontumor tissues." (PMID 30085405, 2018). "Importantly, in ΔCam × N3 double-tg mice even though thymocytes were accumulated at the DN3 stage, still they were not tumorigenic suggesting a strong tumour-preventing activity of NFATc1 in this experimental model." (PMID 27312418, 2016). "Since we showed that the NFATc1 inhibitor CsA treatment significantly decreased the mRNA levels and surface expression of PD-1 in wild-type CD8+ CTLs (Fig3D), we tested whether in vitro targeting NFATc1 in CD8+ CTLs could increase anti-tumor responses." (PMID 25851535, 2015).
tumor (continued). "However, NFATc1 expression in tumor microenvironment was not discussed in earlier experiments." (PMID 34181355, 2021). "We analyzed the biological significance of IL-1 in tumor-induced osteoclastogenesis and clarified that IL-1 stimulated osteoclastogenesis induced by OSCC cells from OPCs without affecting the expression of NFATc1." (PMID 36614130, 2022). "Taken together, these findings suggested that the lack of tumor regression after HPE may be associated with a change in the immunological microenvironment, such as the decrease in the activity of CD56 (+) NK cells, lack of macrophage activity, and decrease in the expression of NFATc1." (PMID 30999581, 2019). "We first examined messenger RNA (mRNA) expression of NFAT family members (NFATc1, NFATc2, NFATc3, NFATc4, and NFAT5) in 30 pairs of HCC tumor tissues (T) and corresponding adjacent nontumor tissues (NT) by qRT‐PCR." (PMID 30085405, 2018). "Furthermore, increased nuclear NFATC1 levels were observed in high RANK expression CRC tissues compared with those in matched normal tissues and tumor tissues with negative RANK expression, as revealed by immunofluorescence staining." (PMID 33795653, 2021).
cancer (82 papers, 2010 to 2026). A tumor composed of atypical neoplastic, often pleomorphic cells that invade other tissues. "In SMAD4-deficient cancer cells, disruption of this interaction liberates NFATc1, enabling activation of oncogenic pathways such as STAT3 signaling." (PMID 40856537, 2026). "Conversely, the expression of NFATc1 is suppressed in several types of cancer, and a reduction of NFATc1 has been shown to be linked with aggressiveness and malignancy of cancer." (PMID 35163061, 2022). "NFATC1, a nuclear factor of activated T-cells c1, is also upregulated in H295R-PM-Ptc+ cells and is associated with malignancy in several cancer models." (PMID 35631574, 2022). "It has been reported that NFAT family including NFATc1, NFATc2, NFATc3, and NFATc4 were closely associated with many kinds of cancers." (PMID 31823518, 2020). "It is well known that nuclear factor of activated T cells c1 (NFATc1) expression is closely associated with progression of many cancers." (PMID 31823518, 2020). "Wnt pathway, which is known to regulate transcription activity and cause aberrant cell division and migration associated with cancer formation, was found indeed deregulated as documented by the downregulation of Wnt2, Nfatc1, and Nfatc4 genes." (PMID 26559525, 2015). "It is noteworthy, that some of the transcription factors which have been previously linked to EZH2 activation, albeit in other cancer entities, underlie transcriptional control by NFATc1 (MYC, STAT3) or represent well-characterized NFATc1 partner proteins (STAT3, ELK1)." (PMID 34943970, 2021). "NFATc1 overexpression has been reported to be associated with poor prognosis in some cancers." (PMID 33800389, 2021). "NFATc1 has many functions in cancer and has been linked to regulation of the c-Myc oncogene." (PMID 22853725, 2012). "The transcriptional regulation of MARCH8 by NFATc1 presents an intriguing area for exploration beyond cancer biology." (PMID 41023307, 2025). "By harnessing the full potential of NFATc1 and c-Jun as therapeutic targets, we can envision a future where targeted immunotherapies transform the landscape of immune-related disorders and cancer treatment." (PMID 40688507, 2025). "NFATc1 is also related to endothelial-mesenchymal transdifferentiation (EMT), a process implicated in cancer metastasis and lymphangiogenesis." (PMID 39822413, 2024). "TGF-β/TGFbr1 is required for the effects of cancer cells on NFATc1 nuclear accumulation and osteoclastogenesis." (PMID 36593458, 2023). "To investigate the association between NFATC1/2 and CD8 + T cells exhaustion, we analyzed CD8 + T cells from pan-cancer scRNA-seq data." (PMID 37833788, 2023). "CD8+ cytotoxic T cells had elevated expression of the cytotoxic markers PD-1, Gzmb, Gzmk, Prf1, Nkg7, Eomes, Irf8, Klrd1, Fyn, Nfatc1, Tnfrsf9, and Zap70, supporting their killing function against cancer cells." (PMID 37762216, 2023). "miR-21 is considered an onco-miR since it is expressed in serum of many cancer patients and it has been correlated with cancer progression and OC differentiation by e.g. NFATc1 promotion amongst other mechanisms." (PMID 36890825, 2023). "Numerous reports about the upregulation of L-type VGCC in several cancers including our results clearly indicate that Cav1.2-mediated Ca2+ influx promotes the nuclear translocation of NFATc1, that is followed by leading to an increase of AM cell proliferation." (PMID 36057617, 2022). "Quantitative PCR showed that NFATc1 was up-regulated in all cancer cell lines apart from SUIT-2; the effect was strongest in PANC-1." (PMID 34572796, 2021). "Among these five isoforms, high expression of NFATc1 has often been determined in many types of cancers such as hepatic, pulmonary and pancreatic carcinomas, compared with their corresponding benign tissues." (PMID 31823518, 2020).
cancer (continued). "Among them, six transcription factors regulating the cancer stem cell-associated genes were verified by the reported literatures (marked with deep red), including NR4A1, FOS, KLF-4, GLI1, NFATC1 and JUN." (PMID 32242101, 2020). "NFATc1 is highly expressed in aggressive cancer cells and tissues, and promotes invasion through the transcriptional induction of Snail and Zeb1 in a TGF-β independent manner." (PMID 30534207, 2018). "So, the effect on tumorigenesis and cancer migration likely depended on the differential activation of NFATc1 and NFATc2 in different cancers." (PMID 28235034, 2017). "PPP3CA is reported to interact with NFATs (NFATc1, NFATc2, NFATc3 and NFATc4) transcriptional factors, and have a crucial role in the regulation of immune response, and invasiveness of cancer cells." (PMID 28881575, 2017). "Potential downstream targets of NFATc1 for its regulation of cancer cell growth include c-myc, COX-2, and autotaxin, all of which are known to involve stimulation of cancer cell proliferation and invasion, chemotaxis, and/or metastasis." (PMID 25638160, 2015). "Expression levels of NFAT isoforms, especially NFATc1, have been assessed in several types of cancer tissue specimens." (PMID 25638160, 2015). "In these studies, localization of NFATc1 detected by immunohistochemical staining (i.e. nuclear vs. cytoplasmic signals) appeared to be cancer type-dependent." (PMID 25638160, 2015). "The role of increased NFATc1 expression on the growth inhibitory effect of P-S on cancer growth was evaluated by silencing or by overexpressing it both in vitro and in vivo." (PMID 24284479, 2014). "Although nuclear factor of activated T-cells c1 (NFATc1) promotes oncogenesis in various cancers, its role in metabolic reprogramming remains unclear." (PMID 41203626, 2025). "Within the NFAT family, NFATc1 has several functions in the regulation of cancer cells." (PMID 38926604, 2024). "Indeed, calcineurin and NFATc1 depletion inhibits cell cycle progression in several types of cancer cells." (PMID 38926604, 2024). "Accordingly, gallium compounds, which are already in several phase II trials, might be considered as an addition to the current regimens for treatment of BL and other cancers, where nuclear NFATc1 expression is evident." (PMID 37546418, 2023). "Moreover, NFATc1 participates in cancer infiltration and metastasis by inducing angiogenesis and lymphangiogenesis through the up-regulation of cyclooxygenase 2, vascular endothelial growth factor (VEGF), and CXC chemokine receptor 7 expression." (PMID 33800389, 2021). "The pivotal role of NFATc1 in the activation of EMT transcriptional programs in cancer cells and the availability of specific small molecule inhibitors (e.g. CsA or VIVIT) renders this factor very interesting as a potential drug target to increase conventional therapies efficiency." (PMID 34845197, 2021). "Both PIM kinases and NFATC1 have been reported to promote cancer cell migration, invasion and angiogenesis, but it has remained unclear whether the effects of NFATC1 are phosphorylation-dependent and which downstream targets are involved." (PMID 31730483, 2019). "However, one of the family members, NFATC1, has also been shown to act as an oncogene that promotes cancer cell proliferation and transformation." (PMID 31730483, 2019). "More fundamentally, we have identified a previously unrecognized calcineurin—mTORC1—NFATc1 phosphorylation and dephosphorylation signaling cascade, which may exert widespread impact on many fields including cancer and immunity." (PMID 30271915, 2018). "Finally, we identified a fundamentally important signaling cascade by which calcineurin inhibits mTORC1, thus blocking its inhibition of NFATc1, which will have broad and long-reaching impact in multiple fields such as bone, immunology and cancer." (PMID 30271915, 2018).